NUDT1 (nudix hydrolase 1)
Description:
Oxidized purine nucleoside triphosphate hydrolase which is a prominent sanitizer of the oxidized nucleotide pool. Catalyzes the hydrolysis of 2-oxo-dATP (2-hydroxy-dATP) into 2-oxo-dAMP. Also has a significant hydrolase activity toward 2-oxo-ATP, 8-oxo-dGTP and 8-oxo-dATP. Through the hydrolysis of oxidized purine nucleoside triphosphates, prevents their incorporation into DNA and the subsequent transversions A:T to C:G and G:C to T:A. Also catalyzes the hydrolysis of methylated purine nucleoside triphosphate preventing their integration into DNA. Through this antimutagenic activity protects cells from oxidative stress.
Synonyms: MTH1
Tractability: Small molecule: a structure with a bound ligand is known; a high-quality ligand is known; it has a binding pocket of medium quality. PROTAC: ubiquitination databases record sites on it; its protein half-life has been measured; a small molecule that binds it is known.
Target class: Enzyme; Hydrolase
Chemical probes: BAY-707 (high quality)
Gene: Protein-coding gene on chromosome 7 (2,242,203 to 2,251,824, forward strand). Ensembl gene ENSG00000106268.
Subcellular location: Cytoplasm, cytosol (Isoform p18); Mitochondrion matrix; Nucleus; Mitochondrion matrix (Isoform p26)
Subcellular location (Human Protein Atlas): Cytosol
Pathways (Reactome):
Metabolism: Phosphate bond hydrolysis by NUDT proteins
Gene Ontology:
Molecular function: 2-hydroxy-ATP hydrolase activity; 2-hydroxy-dATP hydrolase activity; 8-oxo-7,8-dihydrodeoxyguanosine triphosphate pyrophosphatase activity; 8-oxo-7,8-dihydroguanosine triphosphate pyrophosphatase activity; ATP diphosphatase activity; dATP diphosphatase activity; hydrolase activity, acting on acid anhydrides, in phosphorus-containing anhydrides; N6-methyl-(d)ATP hydrolase activity; O6-methyl-dGTP hydrolase activity; protein binding; 5'-(N(7)-methylguanosine 5'-triphospho)-[mRNA] hydrolase activity; snoRNA binding; hydrolase activity
Biological process: DNA protection; purine nucleoside catabolic process; DNA repair; response to oxidative stress
Cellular component: cytoplasm; cytosol; mitochondrial matrix; mitochondrion; nucleus
Genetic constraint (gnomAD): Loss-of-function variants: 20 observed, 16.41 expected, observed/expected ratio (o/e) 1.22, 90% interval 0.86 to 1.74. The upper end of that interval is the gene's LOEUF score, 1.74, which puts it in group 6 of 6, group 1 being the genes least tolerant of losing a copy. Missense variants: 234 observed, 218.09 expected, observed/expected ratio (o/e) 1.07, 90% interval 0.96 to 1.2. Synonymous variants: 101 observed, 87.84 expected, observed/expected ratio (o/e) 1.15, 90% interval 0.98 to 1.36.
Homologues: Orthologues: chimpanzee NUDT1 (99% identical), macaque NUDT1 (97% identical), pig NUDT1 (89% identical), rabbit NUDT1 (85% identical), guinea pig NUDT1 (85% identical), rat Nudt1 (84% identical), mouse Nudt1 (83% identical), zebrafish nudt1 (70% identical), tropical clawed frog nudt1 (69% identical), dog NUDT1 (62% identical). Paralogues in human: NUDT18 (26% identical), NUDT12 (24% identical), NUDT17 (19% identical).
Diseases named in the same sentence as NUDT1 in open-access papers:
NUDT1 is named in the same sentence as 99 diseases in open-access papers, as found by Europe PMC text mining. Sharing a sentence is not in itself a finding about the gene and the disease. The quoted sentences say what the papers report.
gastric cancer (19 papers, 2015 to 2025). A primary or metastatic malignant neoplasm involving the stomach. "For example, miR-485-5p plays a tumor-suppressive role in gastric cancer by targeting nucleoside diphosphate-linked moiety X-type motif (NUDT1)." (PMID 34594577, 2021). "NUDT1 overexpression has been documented in several cancers, including renal-cell carcinomas, brain tumors, lung cancer, gastric cancer, and esophageal squamous cell carcinomas." (PMID 32341205, 2020). "Moreover, the inhibitor of NUDT1 yielded an anti-cancer effect in gastric cancer by decreasing mitochondrial function." (PMID 36814293, 2023). "It has also been revealed that NUDT1 may serve as a predictor of poor prognosis in several tumor types such as gastric carcinoma, colon carcinoma, and oral squamous carcinoma." (PMID 37848855, 2023). "In gastric cancer, miR-485-5p was related to prognosis and overall survival of gastric cancer patients and exerted a suppressor in gastric cancer cell growth and motility by inhibiting NUDT1." (PMID 34512753, 2021). "However, the mechanisms underlying gastric carcinogenesis and the dys-regulation of NUDT1 in gastric cancer (GC) remain unknown." (PMID 29075149, 2017). "Another cohort consisted of 40 gastric carcinoma patients from the Tianjin Medical University Cancer Institute and Hospital was then used to explore the expression level of NUDT1 and its relationship with clinicopathological characteristics by using IHC assays." (PMID 29075149, 2017). "Gastric cancer tissues and paired noncancerous tissue samples were collected, and the expression level of NUDT1 and miR-485-5p were detected." (PMID 29075149, 2017). "In our present study, miR-485-5p and NUDT1 levels showed opposite trends in 5 pairs of gastric carcinoma and noncancerous tissues." (PMID 29075149, 2017). "For example, miR-145 has been found to inhibit cancer cell growth, invasion, and metastasis by suppressing EGFR and NUDT1 in lung adenocarcinoma, FSCN-1 in esophageal squamous cell carcinoma, N-cadherin in gastric carcinoma, and IGF in hepatocellular carcinoma." (PMID 26514209, 2015).
lung carcinoma (15 papers, 2012 to 2022). "High expression of NUDT1 in tumor tissues is associated with worse overall survival (OS) and progression-free survival (PFS) of lung cancer patients." (PMID 32341205, 2020). "Increasing evidence suggests that microRNAs are involved in EGFR-mediated signaling pathways in lung cancers, including miR-145, which is downregulated and associated with TKI resistance targeting ERK, AKT, Oct4, c-MYC, EGFR, and NUDT1." (PMID 31619200, 2019). "Other studies showed that miRNA-145 expression reduced in lung cancer cells, causing elevated c-MYC, NUDT1, OCT4 and EGFR expression, increased tumor cell proliferation, metastasis and migration." (PMID 31554377, 2019). "Studies have demonstrated that miRNA-145 inhibits the expression of its targets, nucleoside X-type motif-1 (NUDT-1), c-Myc, eIF4e and CDK4, supporting a tumor suppressor function of miRNA-145 in lung cancer." (PMID 31554377, 2019). "He discovered that miR-145 plays an important role in inhibiting lung cancer proliferation by targeting EGFR and NUDT1." (PMID 23369397, 2012).
breast carcinoma (14 papers, 2015 to 2025). "Although breast cancers are extensively studied, investigations specifically focusing on the NUDT1 gene represent a relatively small subset." (PMID 40507948, 2025). "This is further highlighted based on other studies where inhibition of NUDT1 (MTH1) reduced breast cancer cell growth in vitro and in vivo." (PMID 33668737, 2021). "Core metabolic prognostic signatures are identified, comprising NUDT1 and GAPDH in kidney renal cell carcinoma and SQLE, ALG3 and PSPH in two independent breast carcinoma cohorts." (PMID 27358048, 2016). "NUDT1, NUDT2, NUDT5, and NUDT16 were overexpressed in breast cancer tissue." (PMID 40839607, 2025). "The therapeutic potential of NUDT-selective inhibitors has already been shown—NUDT1-selective inhibitors have shown efficacy in multiple studies in vitro and in vivo, and the NUDT5-selective inhibitor TH1457 blocks cell proliferation in breast cancer cells." (PMID 33668737, 2021).
melanoma (13 papers, 2016 to 2025). A malignant, usually aggressive tumor composed of atypical, neoplastic melanocytes. "The result showed that SMARCA4, XAB2 and NUDT1 were potent markers for the overall survival (OS) and disease‐specific survival (DSS) and SMARCA4 was shown to correlate with XAB2 and NUDT1 expression in melanoma patients." (PMID 36317703, 2022).
colorectal cancer (9 papers, 2017 to 2025). A primary or metastatic malignant neoplasm that affects the colon or rectum. "The present retrospective cohort study aimed at investigating whether MLH1,APEX1,MUTYH,OGG1,NUDT1,XRCC5, XPA, and ERCC2 single nucleotide polymorphisms (SNPs) are associated with colorectal cancer (CRC) in Chinese population with Lynch syndrome." (PMID 29664240, 2018). "In conclusion, NUDT1 gene and protein expression is not uniform across studied colorectal cancer tissues." (PMID 40507948, 2025).
glioblastoma (9 papers, 2017 to 2025). The most malignant astrocytic tumor (WHO grade IV). "Furthermore, the reduction in NUDT1 expression in glioblastoma cells led to a marked increase in overall reactive oxygen species levels." (PMID 41009025, 2025). "Indeed, it has been previously shown that the expression levels of NUDT1 (also known as MTH1) are associated with a more aggressive glioblastoma and the expression of MTH1 is essential for glioblastoma cancer stem cells." (PMID 33668737, 2021). "A recent study shows that radiation induces a dose-dependent increase in NUDT1 levels in adult and pediatric glioblastoma cell lines; moreover, migration and invasiveness of the glioblastoma cell lines is inhibited by TH588, a NUDT1 inhibitor." (PMID 32341205, 2020).
glioma (7 papers, 2020 to 2025). A benign or malignant brain and spinal cord tumor that arises from glial cells (astrocytes, oligodendrocytes, ependymal cells). "Among these, EID3, MGMT, PMS1, and NUDT1 were significantly related to the prognosis and survival of glioma patients, and the high-risk score group had a significantly shorter survival time." (PMID 37086071, 2023). "The authors also determined the level of mRNANUDT1 expression in gliomas based on publicly available datasets, and found the mRNA level of NUDT1 was significantly higher in malignant brain tumors than in benign ones." (PMID 40507948, 2025). "It is suggested that NUDT1 may play an important role in tumorigenesis of glioma by activating the expression of HIF-1α." (PMID 37086071, 2023). "Other mitochondrial oxidative-stress-related genes including CTSL, TXNRD2, NUDT1, STOX1, and CYP2E1 have been reported differentially expressed with potential prediction accuracy of glioma." (PMID 39012280, 2024). "NUDT1, also known as MTH1, is overexpressed in GBM, and its silencing significantly alters glioma cell viability." (PMID 36180956, 2022). "Moreover, the variance in expression levels of DCPS, EIF4E1B, NUDT1, and NUDT16L1 between glioblastomas (GBMs) and low-grade gliomas (LGGs) suggests their involvement in the progression of glioma malignancy." (PMID 39061374, 2024). "Moreover, the gene expression level analysis by RT-qPCR suggested that among 10 DDR-related signature genes, HUS1, NUDT1, GADD45G, APEX1 and FAM175A were highly expressed in patients with glioma." (PMID 37086071, 2023).
lung adenocarcinoma (7 papers, 2013 to 2020). A carcinoma that arises from the lung and is characterized by the presence of malignant glandular epithelial cells. "Other studies showed that the down-regulation of miRNA-145 in human lung adenocarcinoma was associated with EGFR amplification and its transfection inhibited cancer cell growth through the suppression of its targets, EGFR and NUDT-1." (PMID 31554377, 2019). "The results indicate that miR-145 is a cell proliferation suppressor in lung adenocarcinoma by targeting EGFR and NUDT1 as an ERK and AKT phosphorylation inhibitor, which enhances gefitinib cytotoxicity in NSCLC." (PMID 31619200, 2019).
hepatocellular carcinoma (6 papers, 2015 to 2025). A malignant tumor that arises from hepatocytes. "Collectively, these findings support the potential of NUDT1 as a promising biomarker candidate for hepatocellular carcinoma (HCC)." (PMID 40507948, 2025). "We investigated the prognostic significance of Nudix hydrolase 1 (NUDT1) in hepatocellular carcinoma (HCC)." (PMID 32341205, 2020). "AP-2α directly regulates transcription of critical DNA repair genes such as TOP2A, NUDT1, POLD1, and PARP1 in hepatocellular carcinoma, thereby facilitating repair of oxidized DNA lesions." (PMID 41373739, 2025). "A previous study showed that NUDT1 expression was correlated with the clinicopathological features, degree of vascular invasion, OS, and disease-free survival (DFS) in hepatocellular carcinoma (HCC) patients." (PMID 36606241, 2022).
Burkitt lymphoma (3 papers, 2020 to 2024). A rare form of malignant mature B-cell non-Hodgkin lymphoma. "NUDT1 depletion similarly elicited robust apoptosis in MYC-overexpressing Burkitt’s lymphoma P493 cells, while administration of tetracycline (Tet) to repress MYC expression significantly inhibited cell death." (PMID 38493213, 2024).
pancreatic cancer (3 papers, 2016 to 2025). "Even though TCGA data point to heavy overexpression of NUDT1 in pancreatic tumors, there have not been many studies that specifically focus on MTH1 in this tissue." (PMID 40507948, 2025).
pulmonary arterial hypertension (3 papers, 2022 to 2024). Pulmonary arterial hypertension (PAH) is a group of diseases characterized by mean pulmonary artery pressure >20 mmHg and elevated pulmonary arterial resistance leading to right heart failure. "Overexpressing NUDT1 in pulmonary arterial hypertension reduces the oxidative stress and DNA damage, hence promoting cell proliferation and reducing apoptosis." (PMID 35096203, 2022). "Nudix hydrolase 1 (NUDT1) and PAH-PASMCs hijack persistent oxidative stress and prevent the incorporation of oxidized nucleotides into DNA, thereby allowing cells to escape apoptosis, proliferate and to some extent participate in vascular remodelling in pulmonary hypertension." (PMID 36506315, 2022).
thyroid cancer (3 papers, 2024 to 2025). "MTH1, namely human MutT homologue 1 (aka NUDT1) prevents oxidative DNA damage through inhibiting the incorporation of oxidatively modified nucleotides, and MTH1 is required for maintaining malignant traits of thyroid cancer cells." (PMID 40647171, 2025).
leukemia (2 papers, 2021 to 2024). A malignant (clonal) hematologic disorder, involving hematopoietic stem cells and characterized by the presence of primitive or atypical myeloid or lymphoid cells in the bone marrow and the blood. "In sharp contrast, Nudt1 deletion significantly delayed leukemia onset and extended the survival of transplanted mice." (PMID 38493213, 2024). "Mice receiving ICN1-expressing Nudt1 WT cells exhibited a rapid increase in the proportion of GFP+ leukemia cells in their peripheral blood and developed overt CD4+CD8+ T-ALL within six weeks." (PMID 38493213, 2024). "NUDT1 mRNA data were also obtained from the Leukemia Lymphoma Molecular Profiling Project (LLMPP) datasets, demonstrating significantly higher transcription level of NUDT1 in ABC and GCB DLBCL subtypes and in BL, but not in FL as compared to healthy donor B cells." (PMID 33737576, 2021).
adrenocortical carcinoma (1 paper, 2024). "In adrenocortical carcinoma (ACC), a novel m7G risk signature consisted of METTL1, NCBP1, NUDT1 and NUDT5 was constructed, and the risk score presented significant correlation with enrichment of glycolysis." (PMID 38531882, 2024).
hypopharyngeal carcinoma (1 paper, 2023). Carcinoma, predominantly squamous cell, arising from the epithelial cells of the hypopharynx. "A total of 37 paired tissue of hypopharyngeal carcinoma (HC) and their adjacent tissue (AT) were validated again with higher NUDT1 mRNA present in HC tissue." (PMID 37848855, 2023).
lymphoma (1 paper, 2021). A malignant (clonal) proliferation of B- lymphocytes or T- lymphocytes which involves the lymph nodes, bone marrow and/or extranodal sites. "Because the specificity of the TH588 inhibitor has been debated, we generated NUDT1 knockout (KO) lymphoma cells using a Mino-Cas9 cell line." (PMID 33737576, 2021).
Lynch syndrome (1 paper, 2018). An autosomal dominant hereditary neoplastic syndrome characterized by the development of colorectal carcinoma and a high risk of developing endometrial carcinoma, gastric carcinoma, ovarian carcinoma, renal pelvis carcinoma, and small intestinal carcinoma. "Our results demonstrated that patients with Lynch syndrome harboring at least one risky genotype in MUTYH, NUDT1, and ERCC2 SNPs were at an increased risk of CRC compared to those without risky genotype." (PMID 29664240, 2018). "Our findings revealed that polymorphisms of DNA repair genes that include NUDT1,ERCC2, and MUTYH are associated with CRC in patients with Lynch syndrome in Chinese population." (PMID 29664240, 2018).
neuroblastoma (1 paper, 2021). Neuroblastoma (NB) is the most common solid, extracranial childhood tumor. "To validate the correlation between C > A substitutions and defects in the 8-oxoG pathway, we created CRISPR-Cas9 knockout clones of MUTYH, OGG1, or NUDT1 in a neuroblastoma cell line (CHP134)." (PMID 34479993, 2021). "Therefore, we analyzed WGS data of our neuroblastoma cohort for CNL and mutation status of MUTYH, OGG1, and NUDT1." (PMID 34479993, 2021).
oral squamous cell carcinoma (1 paper, 2022). "It has been shown that patients with oral squamous cell carcinoma (OSCC) having high expression of NUDT1 have shown a poor survival rate." (PMID 35096203, 2022).
prostate carcinoma (1 paper, 2013). A carcinoma that arises from epithelial cells of the prostate gland. "Additionally, prostate cancer cells were treated with anti-β2-M Ab (10 μg/ml) for 24 h and the protein levels of DNA repair enzymes MPG and NUDT1 were examined." (PMID 23874600, 2013).
renal carcinoma (1 paper, 2022). A carcinoma arising from the epithelium of the renal parenchyma or the renal pelvis. "Based on these results, we hypothesized that loss of NUDT1 could lead to apoptosis in renal cancer cells." (PMID 35096203, 2022). "Furthermore, we determined the effects of NUDT1 loss on renal cancer cell lines by using siRNA mediated inhibition." (PMID 35096203, 2022).
thyroid tumor (1 paper, 2025). A benign or malignant neoplasm affecting the thyroid gland. "Even though the levels of NUDT1 were very variable between the patients, results showed a significant overexpression of mRNANUDT1 in thyroid tumors, relative to controls." (PMID 40507948, 2025).